SFN (stratifin)
Description:
Adapter protein implicated in the regulation of a large spectrum of both general and specialized signaling pathways. Binds to a large number of partners, usually by recognition of a phosphoserine or phosphothreonine motif. Binding generally results in the modulation of the activity of the binding partner. Promotes cytosolic retention of GBP1 GTPase by binding to phosphorylated GBP1, thereby inhibiting the innate immune response. When bound to KRT17, regulates protein synthesis and epithelial cell growth by stimulating Akt/mTOR pathway (By similarity). Acts to maintain desmosome cell junction adhesion in epithelial cells via interacting with and sequestering PKP3 to the cytoplasm, thereby restricting its translocation to existing desmosome structures and therefore maintaining desmosome protein homeostasis. Also acts to facilitate PKP3 exchange at desmosome plaques, thereby maintaining keratinocyte intercellular adhesion.
Synonyms: YWHAS
Tractability: Small molecule: a structure with a bound ligand is known; a high-quality ligand is known; it has a binding pocket of medium quality. Antibody: UniProt places it where antibodies can reach, with high confidence; its Gene Ontology location is reachable by antibodies, with medium confidence. PROTAC: UniProt records ubiquitination sites on it; ubiquitination databases record sites on it; a small molecule that binds it is known.
Gene: Protein-coding gene on chromosome 1 (26,863,149 to 26,864,456, forward strand). Ensembl gene ENSG00000175793.
Subcellular location: Cytoplasm; Nucleus; Secreted
Subcellular location (Human Protein Atlas): Cytosol; Mid piece; Nucleoli rim; Nucleoplasm; Predicted to be secreted
Pathways (Reactome):
Gene expression (Transcription): Regulation of localization of FOXO transcription factors
Disease: SARS-CoV-1 targets host intracellular signalling and regulatory pathways; SARS-CoV-2 targets host intracellular signalling and regulatory pathways
Cell Cycle: Chk1/Chk2(Cds1) mediated inactivation of Cyclin B:Cdk1 complex
Immune System: Regulation of GBP-mediated host defense
Programmed Cell Death: Activation of BAD and translocation to mitochondria
Signal Transduction: RHO GTPases activate PKNs
Vesicle-mediated transport: Translocation of SLC2A4 (GLUT4) to the plasma membrane
Gene Ontology:
Molecular function: cadherin binding; identical protein binding; phosphoserine residue binding; protein binding; protein sequestering activity; protein kinase binding; protein kinase C inhibitor activity; phosphoprotein binding
Biological process: intrinsic apoptotic signaling pathway in response to DNA damage; negative regulation of innate immune response; negative regulation of protein localization to plasma membrane; positive regulation of cell adhesion; positive regulation of protein localization; regulation of cell-cell adhesion; regulation of protein localization; release of cytochrome c from mitochondria; establishment of skin barrier; intracellular protein localization; keratinocyte differentiation; negative regulation of protein kinase activity; positive regulation of epidermal cell differentiation; positive regulation of hippo signaling; positive regulation of keratinocyte differentiation; regulation of epidermal cell division; signal transduction; cAMP/PKA signal transduction; positive regulation of cell growth; positive regulation of protein export from nucleus; protein export from nucleus
Cellular component: cytoplasm; cytosol; extracellular exosome; nucleus; extracellular region
Genetic constraint (gnomAD): Loss-of-function variants: 5 observed, 20.33 expected, observed/expected ratio (o/e) 0.25, 90% interval 0.13 to 0.52. The upper end of that interval is the gene's LOEUF score, 0.52, which puts it in group 2 of 6, group 1 being the genes least tolerant of losing a copy. Missense variants: 287 observed, 352.49 expected, observed/expected ratio (o/e) 0.81, 90% interval 0.74 to 0.9. Synonymous variants: 130 observed, 151.79 expected, observed/expected ratio (o/e) 0.86, 90% interval 0.74 to 0.99.
Homologues: Orthologues: chimpanzee SFN (100% identical), macaque SFN (99% identical), mouse Sfn (98% identical), pig SFN (97% identical), guinea pig SFN (97% identical), rat Sfnl1 (96% identical), zebrafish ywhaqa (69% identical), zebrafish ywhaqb (69% identical), tropical clawed frog ywhaq (68% identical), Caenorhabditis elegans par-5 (65% identical), Drosophila melanogaster 14-3-3zeta (65% identical), Caenorhabditis elegans ftt-2 (62% identical). Paralogues in human: YWHAZ (70% identical), YWHAQ (69% identical), YWHAB (67% identical), YWHAG (63% identical), YWHAH (62% identical), YWHAE (60% identical).
Diseases named in the same sentence as SFN in open-access papers:
SFN is named in the same sentence as 110 diseases in open-access papers, as found by Europe PMC text mining. Sharing a sentence is not in itself a finding about the gene and the disease. The quoted sentences say what the papers report.
breast carcinoma (33 papers, 2005 to 2025). "For instance, NDST1, FRZB, ALAD, EDNRB, SSX2IP, and SFN have strong associations with breast cancer development, which bolsters our confidence in the viability of our model." (PMID 38007443, 2023). "We sought to carry out mutation analysis of FANCD2, BRIP1/BACH1, LMO4 and SFN in a large number of non-BRCA1/2 breast cancer families." (PMID 16280053, 2005). "SFN is considered a tumor suppressor in approximately 80% of breast tumors, and its expression in normal mammary epithelial cells has been found to be associated with malignant phenotypes in two basal-like breast cancer progression models." (PMID 37946061, 2024). "The invasion and migration of breast cancer cells may be associated with the upregulation of SFN through silencing of profilin A." (PMID 37946061, 2024). "Furthermore, low SFN expression levels were associated with the decreased overall survival of breast cancer patients, specifically within the HER2-enriched human subtype, most consistent with a loss-of-function, tumour suppressive role of SFN." (PMID 27374210, 2016). "We hypothesized that germline mutations in FANCD2, BRIP1/BACH1, LMO4 and SFN may account for some of the unexplained multiple-case breast cancer families." (PMID 16280053, 2005). "Overall, SFN, YWHAB, TXNDC12, MYL6B, and PRDX4 expressions are significantly associated with breast cancer patient survival." (PMID 37128318, 2023). "SFN (stratifin, also known as 14-3-sigma) has been found to be hypermethylated and related to cell-cycle regulation in human breast cancer cells." (PMID 32156290, 2020). "Differential SFN expression patterns have been found in breast cancer cell lines and primary breast carcinomas." (PMID 30404157, 2018). "Conversely PCDHGB7 and SFN exhibited better sensitivities in breast cancer (55.60% and 73.51%), but the specificity was unsatisfied." (PMID 26918343, 2016). "It appears unlikely, therefore, that FANCD2, BRIP1/BACH, LMO4 and SFN account for more than a small proportion of inherited forms of breast cancer." (PMID 16280053, 2005). "SFN is markedly down-regulated in breast cancer tissue compared to normal mammary epithelium but to our knowledge has not been evaluated for germline mutations in familial breast cancer." (PMID 16280053, 2005). "The increased expression of SFN may also predict a poor prognosis in several cancers, including nasopharyngeal, esophageal, oral, and breast carcinoma." (PMID 40004538, 2025). "In breast cancer cells, the expression of SFN is silenced by methylations." (PMID 40043049, 2025). "Other experiments have also concluded that SFN expression facilitates breast cancer invasion." (PMID 37946061, 2024). "Hence, YWHAB and SFN are strong blood-based breast cancer biomarker candidates and tools for understanding TME regulation." (PMID 37128318, 2023). "Thus, only MYL6B, YWHAB, and SFN expression in breast cancer blood reflected secretory protein expression." (PMID 37128318, 2023). "Data extracted from the Human Protein Atlas showed that YWHAB, SFN, and TXNDC12 expression could distinguish early and late-stage breast cancer in various breast cancer subtypes and are associated with poor patient survival." (PMID 37128318, 2023). "Both YWHAB and SFN are upregulated in breast cancer blood samples and could be found in blood plasma at the highest level of protein certainty." (PMID 37128318, 2023). "Our findings reveal the context-dependent role of SFN (14-3-3σ) in human breast cancer." (PMID 27374210, 2016). "To address this, we set out to determine whether deletion of SFN promotes or inhibits tumorigenesis in the human HER2-enriched breast cancer subtype." (PMID 27374210, 2016). "We found an inverse association between SFN mRNA expression levels and the protein levels of HER2, as well as that of multiple other proteins in the HER2 pathway, both in human breast tumours and in human breast cancer cell lines." (PMID 27374210, 2016).
breast carcinoma (continued). "In contrast, other studies have reported the downregulation of SFN expression in breast cancers." (PMID 25167778, 2014). "Mutation analysis of the BRCA1-interacting genes FANCD2, BRIP1/BACH, LMO4 and SFN in a large number of non-BRCA1/2 breast cancer families did not identify any highly penetrant, pathogenic mutations." (PMID 16280053, 2005). "Stratifin (SFN; 14-3-3 σ; HME1) was first identified by serial analysis of gene expression (SAGE) analysis as an epithelial specific marker that was expressed at seven-fold lower levels in breast cancer cells compared to normal breast epithelium." (PMID 16280053, 2005). "YWHAB, SFN, and MYL6B are upregulated in breast cancer patient's blood, showing biomarker potential." (PMID 37128318, 2023). "It ranks the importance of hub-gene in ARG subgroups identification, and the top3 genes are SFN, TJP3 and TACSTD2, amongst while only TJP3 (HR = 1.95, p = 1.3e-8) is prognosis-related gene in breast cancer." (PMID 37950731, 2023). "We found that the mechanism between SFN and CDK2 in subnetwork 16 was supported by observations that SFN is a frequently hypermethylated gene emerging as a new inhibitor of CDK2 in breast cancer cells." (PMID 36418365, 2022). "In summary, the six-marker panel with HOXD13, SFN, RASSF1a, P16, PCDHGB7, and hMLH1 exhibits significantly aberrant methylation in serum cfDNA from breast cancer patients compared with both age-matched healthy women and women with a benign breast disease." (PMID 26918343, 2016). "14-3-3σ, also known as stratifin or HME1, was originally identified as an epithelial-specific marker downregulated in breast cancer cell lines." (PMID 21559267, 2011). "SFN and CDH1 methylation have been reported in peripheral blood cells as well as in infiltrating leukocytes in breast cancer." (PMID 18702824, 2008). "The peptides upregulate suppressors NR3C1, BRCA1, BRCA2, SFN, and RB1, which may initiate apoptosis processes and growth regulation in breast cancer cells, potentially preventing tumor progression." (PMID 40043049, 2025). "YWHAB has an oncogenic role in cancer, and SFN (14-3-3σ) is typically documented as a tumor suppressor, although the roles of SFN in breast cancer are not so clear." (PMID 37128318, 2023). "Therefore, identified upregulated secretory markers YWHAB, SFN, TXNDC12, and MYL6B show strong potential in establishing a battery of breast cancer biomarkers alongside pri-miR526b and pri-miR655." (PMID 37128318, 2023). "Accumulating data on these methylation markers including the six genes tested in this study (HOXD13, SFN, RASSF1a, P16, PCDHGB7, and hMLH1) is of interest for further evaluation as serum- or serum-based biomarkers for the detection and monitoring of breast cancer patients." (PMID 26918343, 2016). "The genes we selected, SFN, P16, hMLH1, PCDHGB7 and RASSF1a had the most frequency of methylation in breast cancer samples in our previous research and the methylation of some of the genes happened at the early stage of breast cancer." (PMID 26918343, 2016). "We therefore hypothesized that germline mutations in the BRCA1-interacting genes, FANCD2, BRIP1/BACH1, LMO4 and SFN, may account for some non-BRCA1/2 multiple-case breast cancer families." (PMID 16280053, 2005). "Of most interest was the fact that SFN hypermethylation was also detected in the histologically normal adjacent breast epithelium in patients with breast cancer, suggesting that methylation of this gene may be an early event in breast cancer development." (PMID 16280053, 2005). "Although the expression level of SDHC was not significantly downregulated in the breast cancer tissues, the trend of SDHC expression was consistent with that of RWDD4, SEPT7, and SFN expression." (PMID 32156290, 2020).
breast carcinoma (continued). "In this study, we assessed the promoter methylation of an six-gene panel (SFN, P16, hMLH1, HOXD13, PCDHGB7 and RASSF1a) in serum samples by using MethyLight, to investigate whether it could be used for diagnosis of breast cancer or not." (PMID 26918343, 2016).
lung carcinoma (15 papers, 2015 to 2026). "RESULTS: Eight PANoptosis-related genes (DAPK2, CAV1, PDK4, IL3RA, NOTCH1, CHMP4B, IRAK1, and SFN) were identified as being significantly associated with lung cancer." (PMID 41760846, 2026). "Significant loss of SFN expression has also been documented in human hepatocellular carcinoma, lung cancer, oral cancer, prostate cancer, ovarian cancer and gliomas." (PMID 30404157, 2018). "Besides, associated with OCIAD2, immunocytochemical staining for SFN could also increase diagnostic sensitivity for lung cancers." (PMID 33742334, 2021). "Besides, combined with OCIAD2, immunocytochemical staining for SFN could also enhance diagnostic sensitivity for lung cancers." (PMID 30926680, 2019). "Up-regulation of SFN expression is associated with cisplatin chemotherapy failure and poor prognosis in NSCLC, and it regulates lung cancer progression through the induction of autophagy by nucleating Vps34-BECN1-TRAF6 complex." (PMID 37845004, 2023). "A recent study demonstrated that SFN overexpression stimulated tumor initiation and progression of lung cancer." (PMID 35936690, 2022). "SFN (stratifin) participates in the development and progression of lung cancer and stabilizes both EGFR and MET by interacting with ubiquitin-specific protease 8 (USP8)." (PMID 33023006, 2020). "Especially for lung cancer, several studies demonstrated that SFN played as a novel oncogene, stimulating the tumor initiation, and progression of lung adenocarcinoma." (PMID 30926680, 2019). "circFAM190B targets SFN and regulates its ubiquitination, thereby inhibiting cellular autophagy through the SFN/mTOR/ULK1 pathway and ultimately promoting lung cancer development." (PMID 40860147, 2025). "In addition, stratifin (SFN), a cell cycle checkpoint protein and a regulator of mitotic translation that is closely related to DNA damage, is reported to facilitate lung cancer development and progression." (PMID 40845073, 2025).
lung adenocarcinoma (13 papers, 2015 to 2026). A carcinoma that arises from the lung and is characterized by the presence of malignant glandular epithelial cells. "The results showed that overexpression of SFN attenuated the drug susceptibility of human lung adenocarcinoma A549 cells to cisplatin in cell counting kit-8 (CCK-8) assays, whereas knockdown of SFN rescued the resistance of A549 cells to cisplatin." (PMID 34553022, 2021). "Moreover, SFN expression was associated with significantly worse outcomes relative to SFN-negative lung adenocarcinoma patients (P = 0.007)." (PMID 35936690, 2022). "Applied to primary lung adenocarcinoma, SpliCOOL-seq identified tumour subclones within the tumour lesion and uncovered novel DNA methylation biomarkers (e.g., FAM124B, SFN, OR7E47P) associated with patient survival." (PMID 41603298, 2026). "Prof. Masayuki Noguchi’s team identified that SFN specifically binds to ubiquitinated protease 8 (USP8) in lung adenocarcinoma cells, enhancing the stabilization of receptor tyrosine kinases (RTKs), including EGFR and MET, through abnormal regulation of USP8." (PMID 37398672, 2023). "As for SFN, it has been demonstrated that it is over expressed in invasive lung adenocarcinoma cell lines, compared to in situ adenocarcinoma or normal lung tissue and it induces proliferation of cancer cells." (PMID 35366267, 2021). "Suppression of SFN expression by siRNA significantly reduced proliferation activity and the S-phase subpopulation of human lung adenocarcinoma cells and blocked tumor development in mice." (PMID 32382578, 2020). "SFN expression showed significant correlations with lymphatic permeation, vascular invasion, and pathological subtype of lung adenocarcinoma." (PMID 30899432, 2019). "In the GSE10072 array, expression levels of CDKN2A, PHLDA2, and SFN are significantly upregulated in lung adenocarcinoma compared to normal lung tissue in several datasets, and NDRG4 is downregulated." (PMID 29285217, 2017). "Suppression of SFN expression in A549 (a human lung adenocarcinoma cell line) by siSFN significantly reduced cell proliferation activity and the S-phase subpopulation." (PMID 26223682, 2015). "In the present study, we demonstrated that SFN is an oncogenic factor playing a role in the initiation and progression of early lung adenocarcinoma." (PMID 26223682, 2015). "Here, we performed an in vivo study to clarify the role of SFN in initiation and progression of lung adenocarcinoma." (PMID 26223682, 2015). "SFN had a high expression of malignant progression in early-stage lung adenocarcinoma." (PMID 33742334, 2021). "Furthermore, our results suggested that SFN was a potential prognostic marker in lung adenocarcinoma patients after ACT." (PMID 34553022, 2021). "Since DNA demethylation-triggered overexpression of SFN has essential functions during the course of lung adenocarcinoma progression, we expect that GORASP2 and ZYG11A might also have some functional association in this tumor." (PMID 30899432, 2019). "However, our analysis of SFN expression in lung adenocarcinoma indicated that it is overexpressed in tumor cells to a greater extent than in normal lung epithelium, and that this overexpression stimulates tumor growth." (PMID 26223682, 2015). "Although the mechanism underlying the function of SFN in lung adenocarcinoma progression has not been proved, further analysis of the molecular network of SFN in lung tumor cells is required." (PMID 26223682, 2015). "On the basis of these findings, we speculate that SFN in lung adenocarcinoma cells might have tissue-specific functions and regulate cell cycle progression in a positive manner." (PMID 26223682, 2015). "Here, we first examined the function of SFN in lung adenocarcinoma cells." (PMID 26223682, 2015). "Furthermore, elevated expression of SFN has been reported in lung adenocarcinoma, and our study also found that SFN may exert oncogenic effects in lung adenocarcinoma." (PMID 29285217, 2017).